TGFA (transforming growth factor alpha)
Diseases named in the same sentence as TGFA in open-access papers (continued):
Sharing a sentence is not in itself a finding about the gene and the disease.
pulmonary fibrosis (45 papers, 2010 to 2025). Chronic progressive interstitial lung disorder characterized by the replacement of the lung tissue by connective tissue, leading to progressive dyspnea, respiratory failure, or right heart failure. "Conversely, mice deficient in TGFα that lack normal EGFR signalling or that are treated with EGFR pathway inhibitors exhibit resistance to bleomycin-induced lung fibrosis." (PMID 30050057, 2019). "Moreover, the observed decreases in small-scale ventilation heterogeneity (SSVH) and tidal volume for CCSP/TGFα animals are associated with lung fibrosis and the loss of organized, functional lung parenchyma." (PMID 41150169, 2025). "Based on transcriptome analysis of survival pathways, we propose that the IPF and TGFα models mediate the development of apoptosis resistance in fibrocytes and myofibroblasts through largely similar mechanisms to cause continuous expansion of fibrotic lesions in pulmonary fibrosis pathogenesis." (PMID 31156440, 2019). "Further, published studies from our laboratory and others showed increased expression and activity of TGFβ signaling during TGFα and bleomycin-induced pulmonary fibrosis." (PMID 38646784, 2024). "We demonstrated that WT1 is downregulated in the postnatal stages of lung development but is upregulated in mesothelial cells in IPF and in a mouse model of TGFα-induced pulmonary fibrosis." (PMID 36769178, 2023). "Chronic conditional expression of TGFα induces pulmonary fibrosis independently of inflammation in adult murine lung." (PMID 33562816, 2021). "Compared to control siRNA, knockdown of WT1 was sufficient to attenuate the expression of AURKB in lung fibroblasts isolated from both IPF and a mouse model of TGFα‐induced pulmonary fibrosis." (PMID 32761869, 2020). "Our results demonstrate that AURKB is upregulated in fibroblasts isolated from fibrotic lung lesions of IPF and a mouse model of TGFα‐induced pulmonary fibrosis." (PMID 32761869, 2020). "We evaluated the in vivo effects of AURKB inhibition by barasertib using mouse models of TGFα‐ and bleomycin‐induced pulmonary fibrosis." (PMID 32761869, 2020). "In a recent study, we demonstrated that the FDA‐approved anti‐fibrotic agent nintedanib inhibited TGFα‐induced pulmonary fibrosis by limiting both fibroproliferation and myofibroblast survival." (PMID 32761869, 2020). "Our lung physiology measurements using FlexiVent have demonstrated that treatment of mice with barasertib improved lung function during TGFα‐induced pulmonary fibrosis." (PMID 32761869, 2020). "Although previous studies identified anti-fibrotic effects of nintedanib in multiple models of pulmonary fibrosis, we observed distinct effects of nintedanib in attenuating established and ongoing pulmonary fibrosis in TGFα mice." (PMID 31156440, 2019). "In particular, we show that nintedanib increases apoptotic clearance of fibrocytes and lung-resident myofibroblasts to attenuate the progression of TGFα-induced pulmonary fibrosis." (PMID 31156440, 2019). "In support, comparative gene expression analyses suggest that apoptosis-linked gene networks similarly dysregulated in both IPF and a mouse model of TGFα-induced pulmonary fibrosis." (PMID 31156440, 2019). "The EGFR pathway has been implicated in lung fibrosis through studies in which transgenic mice that constitutively express TGFα in epithelial cells develop progressive lung fibrosis." (PMID 30050057, 2019). "Our new findings highlight the relevance of using a mouse model of TGFα-induced pulmonary fibrosis to study fibroblast activation in the pathogenesis of fibrotic lung disease." (PMID 31156440, 2019). "We analyzed the apoptotic pathways activated in mesenchymal cells of IPF and in a mouse model of TGFα-induced pulmonary fibrosis." (PMID 31156440, 2019). "Further, the long-term nintedanib therapy attenuated fibrocyte accumulation, collagen deposition, and lung function decline during TGFα-induced pulmonary fibrosis." (PMID 31156440, 2019).
pulmonary fibrosis (continued). "Inhibition of αvβ6 by using function-blocking antibodies in established lung fibrosis in TGFα-overexpressing mice was able to attenuate the continuation of pleural thickening and decline in lung function." (PMID 27139180, 2016). "To evaluate the effects of combined therapy with ARRY and PX-866, we used TGFα transgenic mice which develop progressive and severe pulmonary fibrosis." (PMID 24475138, 2014). "In support, inhibition of mTOR with rapamycin has been shown to prevent the initiation and propagation in a mouse model of TGFα-driven pulmonary fibrosis." (PMID 21660239, 2011). "Among these, TGFα and TGFβ1 have been shown to function as pivotal profibrotic growth factors with evidence of their involvement in fibroblast activation and the development of pulmonary fibrosis in both human subjects and animal models." (PMID 38646784, 2024). "Furthermore, we also used another model of lung fibrosis in which epithelial overexpression of TGFα induces spontaneous pulmonary fibrosis (TGFαOE-induced pulmonary fibrosis)." (PMID 38646784, 2024). "Notably, the haploinsufficiency of WT1 was sufficient to attenuate fibroproliferation, myofibroblast accumulation, and collagen deposition in both TGFα- and bleomycin-induced pulmonary fibrosis in vivo." (PMID 36769178, 2023). "Indeed, in vivo, postnatal mesothelial lung cells were transformed into myofibroblasts in TGFα/WT1CreERT2/mTmG reporter mice during TGFα-induced pulmonary fibrosis." (PMID 36769178, 2023). "In vivo studies using the TGFα‐ and bleomycin‐induced mouse models of pulmonary fibrosis demonstrate that barasertib, a known AURKB inhibitor, attenuates fibroproliferation, myofibroblast survival, and ECM deposition in established and ongoing pulmonary fibrosis." (PMID 32761869, 2020). "Notably, barasertib treatment resulted in improvements in resistance and elastance and prevented a decrease in lung compliance during TGFα‐induced pulmonary fibrosis." (PMID 32761869, 2020). "Our previous studies demonstrate upregulation of multiple growth factors including TGFβ, IL-6, IL-13, amphiregulin and epiregulin in distinct mesenchymal cell subsets such as fibrocytes, lung resident fibroblasts and WT1-positive myofibroblasts during TGFα-induced pulmonary fibrosis." (PMID 31156440, 2019). "Doxycycline-induced overexpression of TGFα in lung epithelia generates progressive lung fibrosis." (PMID 27139180, 2016). "This suggests that in this specific model of TGFα-induced lung fibrosis, the effective abrogation of fibrosis might require the targeting of multiple pathways in order to limit fibrogenesis and altered lung physiology." (PMID 27139180, 2016). "In addition an important role for αvβ6 in the development of lung fibrosis has been demonstrated using β6 null mice and an anti- αvβ6 integrin antibody in the radiation-induced lung fibrosis mouse model and the TGFα induced lung fibrosis model." (PMID 24917820, 2014). "Overexpression of TGFα in the lung epithelium of transgenic mice results in the formation of fibrotic lesions similar to those found in human pulmonary fibrosis, and previous work from our group shows that inhibitors of either the MAPK or PI3K pathway can alter the progression of fibrosis." (PMID 24475138, 2014). "The TGFα mouse model allows in vivo assessment of signaling pathways mediating pulmonary fibrosis." (PMID 24475138, 2014). "Similarly, in the TGFα model used in the current study, in vivo treatment with barasertib either as a preventive or as a therapeutic strategy led to decreased fibroproliferation and myofibroblast accumulation in the pathogenesis of pulmonary fibrosis." (PMID 32761869, 2020). "To determine whether pro-apoptotic gene expression is dysregulated in mesenchymal cells during TGFα-induced pulmonary fibrosis, we used RT-PCR to quantify pro-apoptotic gene expression in lung-resident myofibroblasts and fibrocytes isolated from lungs of normal and TGFα mice on Dox for 4 weeks." (PMID 31156440, 2019).
pulmonary fibrosis (continued). "In summary, data from our study establishes that combined pharmacologic inhibition of the MAPK and PI3K pathways in the TGFα model provides more effective resolution of pulmonary fibrosis.and could potentially enhance the survival of patients with interstitial lung disease." (PMID 24475138, 2014). "We show that fibrosis induced by TGFα is highly dependent on AURKB expression and treating TGFα mice with barasertib, an AURKB inhibitor, reverses fibroblast activation, and pulmonary fibrosis." (PMID 32761869, 2020). "Our previous findings suggest that they accumulate in these lesions rather than in normal-looking areas of the lung during TGFα-induced pulmonary fibrosis." (PMID 31156440, 2019). "Similar to the TGFα model, the rapamycin analog SDZ RAD prevented bleomycin-induced pulmonary fibrosis in rats although it was unclear whether changes in lung inflammation may have contributed to these improvements." (PMID 21660239, 2011). "To determine the role of the SEMA3B-NRP1 axis in preclinical mouse models of pulmonary fibrosis, we quantified the expression of SEMA3B and NRP1 in the lungs of mice with severe fibrotic lung disease in two murine models of pulmonary fibrosis, bleomycin (BLM)-induced, and TGFα-induced lung fibrosis." (PMID 38646784, 2024). "However, incomplete resolution of lung fibrosis with nintedanib therapy and other inhibitors is not unique to the TGFα model." (PMID 31156440, 2019).
colon carcinoma (30 papers, 1990 to 2025). "Transforming growth factor alpha, down-regulated in our patients with a good responsiveness to preoperative therapy, is implicated in metastatic spread of colon cancer cells." (PMID 19356222, 2009). "TMED9 drives colon cancer metastasis via the CNIH4/TGFα/GLI pathway, inducing EMT and enhancing migration/invasion." (PMID 41373732, 2025). "Studies have found that TGFA is considered to promote colon cancer migration and invasion by regulating epithelial‐mesenchymal transition (EMT) markers and the NF‐κB signalling pathway." (PMID 38152044, 2024). "Despite accumulating evidence suggests that the EGFR or transforming growth factor α (TGFα)/ EGFR signaling pathways play a critical role in colon cancer progression, the EGF autocrine loop in colon cancer is still poorly investigated." (PMID 37853459, 2023). "In TMED9 silenced cells, TGFα appeared retained in the GC, which compromises its function, thus resulting in the suppression of colon cancer cells migration and metastasis." (PMID 35805075, 2022). "CNIH4 gene, which encodes a member of CORNICHON family, an evolutionarily conserved TGFα exporter, is essential for metastasis of colon cancer cells." (PMID 33934539, 2021). "In primary colon tumours, aberrant TGFα/EGFR expression helps propagate tumour cells in lymph nodes and the liver." (PMID 28105072, 2016). "The activation of TGFα-EGFR signaling in primary colon tumors contributes to the spread of tumor cells to lymph nodes and the liver." (PMID 23986907, 2013). "Colon cancer cells secrete TGFα in response to hypoxia and the ligand signals, the cell surface EGFR, to initiate a sequence of cell survival programs." (PMID 23986907, 2013). "TGFα-EGFR signaling in colon cancer cells creates a microenvironment that is conducive for metastasis, providing a rationale for efforts to inhibit EGFR signaling in TGFα-positive cancers." (PMID 23986907, 2013). "Previous studies have demonstrated that TGFα activates the MAPK pathway leading to the increased expression of integrin α2 for cellular adhesion in colon cancer cells." (PMID 22864984, 2012). "Furthermore, elevated AREG expression associates with tumor budding, invasion, poor prognosis, and increased sensitivity to EGFR inhibition in HNSCC, while TGFα can confer cetuximab resistance through inducing EGFR-MET interaction in colon cancer." (PMID 41115375, 2025). "Thus, whereas TMED9 levels per se are not significantly correlated with disease-free survival, the levels of mediators and markers we identify - CNIH4 and TGFα- predict colon cancer outcome." (PMID 31253868, 2019). "Crosstalk between TGFα and IL-6 has been demonstrated in an inflammatory colon cancer model." (PMID 25547486, 2014). "Lastly, TMED9 was shown to mediate colon cancer metastases by activating the GLI1, CNIH4 and TGFA regulatory pathway and opposing TMED3-WNT-TCF signaling." (PMID 40497947, 2025). "Researches indicated that CNIH4 potentially increases colon cancer cell metastatic activity by forming a positive feedback loop with TMED9, GLI1, and TGFα." (PMID 37062068, 2023). "A relevant study confirmed that CNIH4 increased the metastatic activity in patients with colon cancer by forming a positive feedback loop involving TMED9, GLI1, and TGFα." (PMID 37062068, 2023). "Once secreted, TGFα activates its receptor EGFR, thus stimulating the ERK, AKT and Hedgehog (HH)-GLI signaling, which culminates in colon cancer cells migration and metastasis." (PMID 35805075, 2022). "Analyses in three colon cancer cell types highlight a TMED9-dependent gene set that includes CNIH4, a member of the CORNICHON family of TGFα exporters." (PMID 31253868, 2019). "TGFα effects were reproduced in LS174T and CC36 cells, suggesting their widespread effects on human colon cancer cells." (PMID 31253868, 2019).
colon carcinoma (continued). "Our data indicate that TGFA and CNIH4, which display predictive value for disease-free survival, promote colon cancer cell metastatic behavior, and suggest that TMED9 pro-metastatic function involves the modulation of the secretion of TGFα ligand." (PMID 31253868, 2019). "Colon cancer cells express high amounts of EGFR and overexpress TGFα in response to hypoxia, triggering a signalling cascade that helps them survive." (PMID 28105072, 2016). "Remarkably, growth factors and receptors FGF2 and IGF1R were identified as common, and PDGFR and TGFA as specific factors contributing to U2OS human osteosarcoma and HCT116 colon cancer cells growth, respectively." (PMID 24023735, 2013). "Growth factors and receptors FGF2, IGF1R, PDGFRB and TGFA were identified as factors contributing selectively to the control of U2OS osteosarcoma and HCT116 colon cancer cell growth." (PMID 24023735, 2013). "In a colon cancer model, REG4 was induced by growth factors, including transforming growth factor-alpha, epidermal growth factor (EGF), basic fibroblast growth factor and hepatocyte growth factor." (PMID 23342005, 2013). "Moreover, WNT-TCF inhibits TMED9, which, in turn, represses WNT-TCF pathway components and drives CNIH4/TGFα/GLI signaling, thus promoting colon cancer metastases." (PMID 35805075, 2022). "Therapeutic interventions that are designed to block EGFR signaling in TGFα-positive colon tumors will likely have a negative impact on a number of processes that are essential for metastasis formation." (PMID 23986907, 2013). "The FET colon cancer cell line which normally does not form subcutaneous xenografts in athymic mice becomes highly tumorigenic after TGFα (transforming growth factor-α) transfection to generate constitutive EGFR (epidermal growth factor receptor) activation." (PMID 22672900, 2012). "Immortalized cell line SW620, deriving from a human lymph node metastasis from an adenocarcinoma of the colon, was selected from a colon carcinoma library for its very low EGFR expression consistent with previous recent findings and low expression of the most common EGFR ligands, including TGFA." (PMID 35612280, 2022).
pancreatic cancer (28 papers, 1990 to 2025). "Certain studies have linked increased expression of TGFα to the pathophysiology of pancreatic cancer." (PMID 40410803, 2025). "Concomitant expression of epidermal growth factor receptor (EGFR) with its ligand, such as EGF, transforming growth factor α (TGFα) or amphiregulin has been associated with decreased patient survival in pancreatic cancer." (PMID 16822304, 2006). "To corroborate that TGFα was a relevant factor in the regulation of pancreatic cancer cell proliferation, we eliminated its expression by CRISPR/Cas9 in three of the pancreatic cancer cell lines, and two clones of each cell line were selected to assess the effect of TGFα loss on cell proliferation." (PMID 40410803, 2025). "In patient-derived xenografts as well as in pancreatic cancer cell lines, multiple molecular forms of TGFα were identified, including the transmembrane TGFα precursor (proTGFα) and the soluble 6 kDa mature form." (PMID 40410803, 2025). "This study investigates the role of transforming growth factor-alpha (TGFα) in pancreatic cancer and its potential as a therapeutic target." (PMID 40410803, 2025). "When conjugated to cytotoxic agents such as MMAF, the resulting antibody-drug conjugates (ADCs) exhibited potent antiproliferative activity, significantly reducing the viability of TGFα-expressing pancreatic cancer cells." (PMID 40410803, 2025). "In vivo, the TGFα-targeting ADCs elicited substantial tumor regression in murine models of pancreatic cancer, whereas the unconjugated antibodies merely stabilized tumor growth." (PMID 40410803, 2025). "In line with in silico data obtained from patient samples, pancreatic cancer cell lines expressed TGFA to levels above those expressed by most of the cell lines available in the database." (PMID 40410803, 2025). "The ADCs, particularly the ones that contained MMAF, demonstrated a significant antiproliferative effect on TGFα-expressing pancreatic cancer cells, with IC50 values significantly lower than those of the free drug or the unconjugated antibodies." (PMID 40410803, 2025). "This study expands on the understanding of TGFα in pancreatic cancer by analyzing its expression and function in both patient-derived tumors and cell lines." (PMID 40410803, 2025). "The expression and molecular forms of TGFα were analyzed in pancreatic cancer cell lines, as well as in patient-derived xenografts (PDXs)." (PMID 40410803, 2025). "TGFα contributes to the desmoplastic reaction (fibrotic tissue formation) observed in pancreatic tumors, which creates a dense stroma that makes the tumor more resistant to therapeutic interventions." (PMID 40410803, 2025). "This study highlights the overexpression and functional significance of TGFα in pancreatic cancer, making it a promising therapeutic target." (PMID 40410803, 2025). "lncRNA LINC00857 acts as a competitive endogenous RNA of miR-340-5p and upregulates the expression of TGFA, thereby, enhancing the malignant behavior of pancreatic cancer cells." (PMID 35647035, 2022). "TGFα in pancreatic cancer cells regulates the proliferation and metastasis of cells through the MAPK pathway." (PMID 26843615, 2016). "Increased expression of EGFR expression with TGFα found upregulated in pancreatic cancer, ovarian cancer, Wilms tumor and other tissues, both of which were positively correlated." (PMID 26843615, 2016). "Overexpression of TGFα has been reported in transformed cells of many cancer types, including the acinar cells and ductal epithelium in human pancreatic cancer." (PMID 25803032, 2015).